CTDNEP1 (CTD nuclear envelope phosphatase 1)
Description:
Serine/threonine protein phosphatase forming with CNEP1R1 an active phosphatase complex that dephosphorylates and may activate LPIN1 and LPIN2. LPIN1 and LPIN2 are phosphatidate phosphatases that catalyze the conversion of phosphatidic acid to diacylglycerol and control the metabolism of fatty acids at different levels. May indirectly modulate the lipid composition of nuclear and/or endoplasmic reticulum membranes and be required for proper nuclear membrane morphology and/or dynamics. May also indirectly regulate the production of lipid droplets and triacylglycerol. May antagonize BMP signaling.
Synonyms: DULLARD; HSA011916; NET56
Tractability: Antibody: UniProt predicts a signal peptide or a membrane-spanning region. PROTAC: ubiquitination databases record sites on it.
Gene: Protein-coding gene on chromosome 17 (7,243,589 to 7,252,841, reverse strand). Ensembl gene ENSG00000175826.
Subcellular location: Endoplasmic reticulum membrane; Nucleus membrane
Subcellular location (Human Protein Atlas): Lipid droplets
Pathways (Reactome):
Cell Cycle: Depolymerization of the Nuclear Lamina
Gene Ontology:
Molecular function: phosphoprotein phosphatase activity; protein binding; protein serine/threonine phosphatase activity; phosphatase activity
Biological process: nuclear envelope organization; positive regulation of triglyceride biosynthetic process; protein dephosphorylation; protein localization to nucleus; mitotic nuclear membrane disassembly
Cellular component: cytoplasm; endoplasmic reticulum membrane; Nem1-Spo7 phosphatase complex; nuclear envelope; nuclear membrane; nucleus
Genetic constraint (gnomAD): Loss-of-function variants: 2 observed, 26.34 expected, observed/expected ratio (o/e) 0.0759, 90% interval 0.03 to 0.24. The upper end of that interval is the gene's LOEUF score, 0.24, which puts it in group 1 of 6, group 1 being the genes least tolerant of losing a copy. Missense variants: 151 observed, 300.52 expected, observed/expected ratio (o/e) 0.5, 90% interval 0.44 to 0.57. Synonymous variants: 117 observed, 116.15 expected, observed/expected ratio (o/e) 1.01, 90% interval 0.87 to 1.17.
Homologues: Orthologues: chimpanzee CTDNEP1 (100% identical), dog CTDNEP1 (99% identical), mouse Ctdnep1 (99% identical), pig CTDNEP1 (99% identical), rat Ctdnep1 (99% identical), macaque CTDNEP1 (98% identical), zebrafish ctdnep1a (91% identical), zebrafish ctdnep1b (89% identical), tropical clawed frog ctdnep1 (86% identical), guinea pig CTDNEP1 (86% identical), Drosophila melanogaster Dd (70% identical), rabbit CTDNEP1 (69% identical), and 1 more. Paralogues in human: CTDSP1 (37% identical), CTDSPL (37% identical), CTDSPL2 (36% identical), CTDSP2 (34% identical), TIMM50 (20% identical).
Diseases named in the same sentence as CTDNEP1 in open-access papers:
CTDNEP1 is named in the same sentence as 12 diseases in open-access papers, as found by Europe PMC text mining. Sharing a sentence is not in itself a finding about the gene and the disease. The quoted sentences say what the papers report.
medulloblastoma (6 papers, 2023 to 2025). A malignant, invasive embryonal neoplasm arising from the cerebellum. "In humans, mutations in CTDNEP1 are frequently observed in aggressive forms of medulloblastoma that display amplification of the C-MYC oncogene." (PMID 40216785, 2025). "Mutations in CTDNEP1 are significantly enriched in MYC-driven medulloblastomas with poor prognosis, suggesting its potential role in cancer development." (PMID 39930152, 2025). "In the future, it will be interesting to explore if these two activities of CTDNEP1 are linked and how they contribute to medulloblastoma progression." (PMID 40216785, 2025). "CTDNEP1 has been identified as a tumor suppressor in highly aggressive Myc-driven medulloblastoma, and its deficiency is associated with poor patient prognosis, presenting a targetable therapeutic opportunity for drug discovery." (PMID 39551141, 2024). "A recent study found that MYC-driven medulloblastomas have the most significantly enriched mutation in CTDNEP1." (PMID 37374122, 2023). "Inactivating mutations in CTDNEP1 correlate with development of medulloblastoma, an aggressive childhood cancer." (PMID 38045299, 2023). "Aggressive medulloblastomas frequently display CTDNEP1 mutations." (PMID 40216785, 2025). "According to a recent study, the loss of CTDNEP1 induces aggressive medulloblastoma." (PMID 37374122, 2023). "Mutations in CTDNEP1 have been discovered in MYC-driven medulloblastomas." (PMID 37374122, 2023). "Ctdnep1 ablation promotes the transformation of murine cerebellar progenitors into Myc-amplified medulloblastomas, resembling their human counterparts." (PMID 36765089, 2023). "Here we report that mutations in CTDNEP1, a CTD nuclear-envelope-phosphatase, are the most significantly enriched recurrent alterations in MYC-driven medulloblastomas, and define high-risk subsets with poorer prognosis." (PMID 36765089, 2023). "Based on these observations, the authors tried to reveal the detailed mechanism of CTDNEP1 as a tumor suppressor in aggressive MYC-driven medulloblastomas." (PMID 37374122, 2023). "CTDNEP1 has several roles in novel biological activities such as neural tube development in embryos, nuclear membrane biogenesis, regulation of bone morphogenetic protein signaling, and suppression of aggressive medulloblastoma." (PMID 37374122, 2023). "Together, our studies demonstrate that CTDNEP1 is a tumor suppressor in highly aggressive MYC-driven medulloblastomas by controlling MYC activity and mitotic fidelity, pointing to a CTDNEP1-dependent targetable therapeutic vulnerability." (PMID 36765089, 2023).
acute myocardial infarction (1 paper, 2018). Necrosis of the myocardium, as a result of interruption of the blood supply to the area. "Previous reports have indicated that the miR-122-5p/miR-133b ratio could as a specific early prognostic biomarker for acute myocardial infarction, and miR-122-5p upregulation can trigger the compensatory response of LPIN1 and CTDNEP1 in hepatosteatosis." (PMID 29467645, 2018).
brain tumors (1 paper, 2023). "A recent study showed that loss of CTDNEP1 can induce aggressive brain tumors." (PMID 37374122, 2023). "CTDNEP1 has been found in an integrative deep sequencing analysis of brain tumor samples." (PMID 37374122, 2023). "Therefore, CTDNEP1 suppresses brain tumors by triggering MYC amplification and genomic instability." (PMID 37374122, 2023).
colon adenocarcinoma (1 paper, 2022). "(B) DNA–RNA and RNA–protein correlations for representative complex and non-complex genes frequently gained (FAM210B and PRPF6) or lost (CTDNEP1 and INPP5K) in colon adenocarcinoma (COAD)." (PMID 36129397, 2022).
Hypertension (1 paper, 2024). The presence of chronic increased pressure in the systemic arterial system. "Furthermore, CTDNEP1 is known to dephosphorylate LPIN1, which is implicated in the development of hypertension." (PMID 39189255, 2024).
tumor (6 papers, 2020 to 2024). "To determine the effect of CTDNEP1 deficiency on tumor cell growth, we inhibited CTDNEP1 expression in different G3-MB tumor cells with or without MYC amplification using lentiviral shRNAs." (PMID 36765089, 2023). "The functional complementation of yeast Nem1 by human CTDNEP1 has been shown, and mutations in CTDNEP1 have been identified in tumor cells." (PMID 37998025, 2023). "Co-targeting MYC and CHEK1 activities synergistically inhibits CTDNEP1-deficient MYC-amplified tumor growth and prolongs animal survival." (PMID 36765089, 2023). "To further determine the potential mechanisms underlying the tumor suppressive effects of CTDNEP1, we performed transcriptome profiling of D425 MB cells transduced with control shRNAs and shCTDNEP1 RNAs." (PMID 36765089, 2023). "To further determine the selectivity of the treatment on the growth of wildtype and CTDNEP1-deficient tumor cells, we treated control or CTDNEP1-knockdown D283 or MB-004 cells with JQ1 and prexasertib." (PMID 36765089, 2023). "Human CTDNEP1 can functionally complement yeast Nem1 and mutations in CTDNEP1 were discovered in tumor cells." (PMID 32599961, 2020). "CTDNEP1 knockdown substantially increased the sensitivity of cells to drug combination treatment compared with control cells, suggesting that this combined treatment more selectively inhibits the growth of CTDNEP1 deficient tumor cells." (PMID 36765089, 2023). "This treatment similarly inhibited cell growth of Ctdnep1-deficient tumor cells." (PMID 36765089, 2023). "We find that JQ1 suppresses MYC transcription and can synergize with CHEK1 inhibitor prexasertib to suppress tumor growth more effectively than either single agent alone, while prolonging survival in the animals bearing CTDNEP1-deficient MYC-amplified MB tumors." (PMID 36765089, 2023). "Ctdnep1 ablation in Nestin+ NPCs causes extensive cell death in the developing brain, which may contribute to animal death prior to tumor formation, suggesting that additional genetic, epigenetic, and other molecular events are necessary prior to full transformation." (PMID 36765089, 2023). "Our data indicate that the growth of Ctdnep1-deficient tumor cells depends on MYC levels, which is in keeping with a critical role of MYC in tumor cell proliferation and chromosome instability." (PMID 36765089, 2023). "CTDNEP1-deficiency-induced tumors resemble the histopathological, transcriptomic, and clinical features of human G3 MB counterparts, suggesting that CTDNEP1 is a potent tumor suppressor in the highly aggressive MYC-driven G3 MBs." (PMID 36765089, 2023). "Our transcriptome profiling analysis indicated a downregulation of mitotic sister-chromatid segregation pathway in Ctdnep1-cKO tumor cells." (PMID 36765089, 2023). "To investigate the effect of CTDNEP1 overexpression on tumor cell growth, we transduced D425 MB cells with a lentivirus overexpressing CTDNEP1." (PMID 36765089, 2023). "The combined treatment with JQ1 and prexasertib elicited synergistic effects on the net cell growth in Ctdnep1-cKO tumor cells across a range of concentrations." (PMID 36765089, 2023). "The strongest Myc amplicon signals at metaphase were detected in two rearranged chromosomes in Ctdnep1-cKO NPCs and Ctdnep1-cKO tumor cells (yellow arrows)." (PMID 36765089, 2023). "CTDNEP1 has recently been reported as a tumor suppressor in aggressive MB." (PMID 39062749, 2024). "In addition, the expression profile of Ctdnep1-cKO-tumor cells exhibited a greater similarity to that of MYC-driven G3 MB mouse models when compared with Ctdnep1-cKO NPCs and control NPCs." (PMID 36765089, 2023). "In addition, an investigation into the action of CTDNEP1 as a tumor suppressor is necessary to distinguish it from other protein phosphatases’ action on tumors." (PMID 37374122, 2023). "In addition, knockdown of CTDNEP1 in patient-derived MB-004 cells accelerated tumor growth and shortened animal lifespan in an orthotopic-engrafted model." (PMID 36765089, 2023).
tumor (continued). "Importantly, combined JQ1 and prexasertib treatment of Ctdnep1-cKO tumor cells at reduced doses was more effective than either single agent." (PMID 36765089, 2023). "In addition, tumors in mice xenografted with CTDNEP1-overexpressing D425 cells were smaller than those grafted with control vector-transduced D425 cells, suggesting that CTDNEP1 overexpression inhibits tumor cell growth." (PMID 36765089, 2023). "This work presents a novel and exciting role of CTDNEP1 as a tumor suppressor." (PMID 37374122, 2023). "Importantly, LOH of CTDNEP1 in the tumor may increase the therapeutic window for combined treatment with MYC and CHEK1 inhibition." (PMID 36765089, 2023). "Notably, the fluorescent in situ hybridization (FISH) assays detected six and four Myc amplicons in the majority of Ctdnep1-cKO tumor cells (17/20) and Ctdnep1-cKO NPCs (14/20) at DIC 70, respectively, compared with the normal two Myc gene copies in control NPCs." (PMID 36765089, 2023). "Indeed, treatment with JQ1 or THZ1 resulted in inhibition of Ctdnep1-cKO tumor cell proliferation." (PMID 36765089, 2023). "Thus, the tumor suppressor activity of CTDNEP1 may be exerted in part by inhibiting MYC activity while maintaining cell-cycle homeostasis and genomic stability." (PMID 36765089, 2023). "Thus, the loss of CTDNEP1 promoted tumor growth of both MYC-amplified and non-MYC-amplified G3-MB cells in xenografts, suggesting a tumor-suppressive role for CTDNEP1 in G3-MBs." (PMID 36765089, 2023). "Moreover, CTDNEP1 knockdown led to significant increases in tumor sphere formation in both MYC amplified (D425) and non-MYC amplified (D283) G3-MB cell lines." (PMID 36765089, 2023). "Despite the increase in MYC target expression in CTDNEP1-deficient cells, MYC mRNA levels were not substantially altered in D425 tumor cells treated with shCTDNEP1 RNAs, suggesting that CTDNEP1 might regulate MYC signaling post-translationally." (PMID 36765089, 2023). "To examine MYC stability, we treated tumor cells with a protein synthesis inhibitor cycloheximide (CHX) and found that both MYC and p-S62-MYC levels remained higher in the MYC-amplified D425 and non-MYC amplified D283 cells with CTDNEP1 knockdown than control-treated cells." (PMID 36765089, 2023).
cancer (4 papers, 2023 to 2025). A tumor composed of atypical neoplastic, often pleomorphic cells that invade other tissues. "Together, this reveals mechanisms for how NEP1R1 regulates CTDNEP1 and explains how cancer-associated mutations inactivate CTDNEP1." (PMID 38045299, 2023). "EPS8L2 was found to interact with Ctdnep1 to cause nuclear mispositioning by regulating dorsal actin cables for nuclear movement during cell migration, which is usually associated with cell dysfunction and disease, from muscular disorders to cancer metastasis." (PMID 36918772, 2023). "By uncovering novel players like CTDNEP1, our study sheds light on the multifaceted nature of DAC’s action and its potential for treating cancers with diverse DNA repair deficiencies." (PMID 39930152, 2025). "Notably, since CTDNEP1 mutations or deletions have also been identified in other cancers, CTDNEP1 might play a broader role in cancer formation serving as a molecular link regulating MYC activity and expression across different cancer types." (PMID 36765089, 2023).
bone disorder (1 paper, 2025). "The CTDNEP1-FLAG precipitates were also highly enriched in MAN1 (also known as LEMD3), an understudied INM resident protein with links to TGFβ/BMP signaling and mutated in bone disorders characterized by excessive TGFβ/BMP signaling." (PMID 40216785, 2025).
CNS tumor (1 paper, 2023). "In addition, CTDNEP1 mutations occur most frequently in MBs compared to other CNS tumor types, and CTDNEP1 expression is lower in MB tumors than normal brain and cerebellar tissues." (PMID 36765089, 2023).
CTDNEP1 also shares sentences with these, for which no sentence is quoted: childhood cancer (1 paper); muscular disorders (1); Neurodevelopmental delay (1).